ERCC1 (ERCC excision repair 1, endonuclease non-catalytic subunit)
Diseases named in the same sentence as ERCC1 in open-access papers (continued):
Sharing a sentence is not in itself a finding about the gene and the disease.
diabetes (2 papers, 2019 to 2022).
dilated cardiomyopathy (2 papers, 2020 to 2023). Cardiomyopathy which is characterized by dilation and contractile dysfunction of the left and right ventricles. "The GO terms enriched for the Ercc1-deficient model mostly specify for extracellular matrix organization and collagen fibril assembling, reflecting the fibrotic tissue deposition accompanying dilated cardiomyopathy, which develops in the hearts of Ercc1-deficient animals." (PMID 32424227, 2020). "Ckmm‐Cre+/−;Ercc1−/fl mice died spontaneously by 7 months of age with severe dilated cardiomyopathy." (PMID 36734200, 2023). "Deleting Ercc1 in cardiac myocytes causes a profound pathologic effect in the heart, leading to dilated cardiomyopathy and sudden death in mice by 6 months of age, independent of any exogenous genotoxin." (PMID 36734200, 2023). "Additionally, deletion of Ercc1 in cardiac myocytes induced marked ventricular interstitial fibrosis at 6 months in Ckmm‐Cre+/−;Ercc1−/fl, consistent with histopathologic changes in dilated cardiomyopathy." (PMID 36734200, 2023).
disc degeneration (2 papers, 2017 to 2020). "Moreover, the ERCC1-deficient mice manifest accelerated disc degeneration with aging due to DNA repair deficiency." (PMID 28392887, 2017). "Interestingly, while exposure to young blood only marginally mitigated age-related IDD in natural aging mice, it significantly reduced disc degeneration in accelerated aging Ercc1-/Δ mice." (PMID 32527988, 2020).
esophageal tumor (2 papers, 2014 to 2020). "ERCC1 negativity, a marker of platinum response, was associated with PD‐L1 expression in GIST tumors (p = 0.032), whereas ERCC1 positivity was associated with PD‐L1 expression in glioblastoma (p = 0.030), female genital tract malignancies (p < 0.001) and esophageal tumors (p = 0.010)." (PMID 31479512, 2020).
gastric adenocarcinoma (2 papers, 2012 to 2018). "In contrast, greater FPRP values were observed for other significant associations between ERCC1 variants and gastric adenocarcinoma, suggesting some possible bias in these positive findings." (PMID 23166636, 2012). "For a prior probability of 0.01, assuming that the OR for specific genotype was 1.50 (risk) or 0.67 (protection), with statistical power of 0.361, the FPRP values were 0.007 for an association of the ERCC1 2–3 risk genotypes, with an increased risk of gastric adenocarcinoma in all individuals." (PMID 23166636, 2012). "In this study, we found that ERCC1 rs2298881C and rs11615A variant genotypes were associated with a pronounced increased risk of gastric adenocarcinoma and that the increased risk associated with 2–3 risk genotypes was more evident in never drinkers, NGCA and clinical stage I+II." (PMID 23166636, 2012). "Similarly, gastric adenocarcinoma patients with low ERCC1 levels showed a greater benefit from cisplatin treatment than those with high ERCC1 levels." (PMID 30208165, 2018). "Three ERCC1 functional SNPs (rs2298881C>A, rs3212986C>A and rs11615G>A) and two XPF/ERCC4 functional SNPs (rs2276466C>G and rs6498486A>C) were genotyped for 1125 gastric adenocarcinoma cases and 1196 cancer-free controls by Taqman assays." (PMID 23166636, 2012).
Hypertension (2 papers, 2022 to 2024). The presence of chronic increased pressure in the systemic arterial system. "DNA damage is an important contributor to the aging process, and mice with a DNA repair defect caused by Ercc1 deficiency display hypertension, vascular stiffening, and loss of vasomotor control." (PMID 38451018, 2024). "It was previously shown that Ercc1 deficient mice display accelerated cardiovascular aging, evidenced by hypertension and vascular stiffness." (PMID 38451018, 2024).
liver failure (2 papers, 2013 to 2025). A liver disease characterized by the liver losing or has lost all of its function. "A functional ERCC1 is essential for survival; knockdown of the ERCC1 gene in mice was observed to lead to an accelerated-aging phenotype, with brain damage, liver failure and death occurring shortly after weaning." (PMID 23426424, 2013). "Unlike NER-deficient mice, mice with mutations in Ercc1 or Xpf develop severe liver dysfunction and die from liver failure." (PMID 40684071, 2025).
mucositis (2 papers, 2017 to 2020). Mucositis is inflammation and damage of the mucous membranes lining the mouth and other parts of the gastrointestinal (GI) tract. "Our literature review identified 27 candidate genes, of which ERCC1, XRCC1, and MTHFR were the most frequently studied for mucositis." (PMID 28678827, 2017).
neuroblastoma (2 papers, 2020 to 2022). Neuroblastoma (NB) is the most common solid, extracranial childhood tumor. "Additionally, several genetic alterations including MEG3 polymorphisms, ERCC1/XPF, and NRAS were associated with the occurrence of neuroblastoma and might serve as important diagnosis biomarkers in the future." (PMID 32695501, 2020).
pancreatic ductal adenocarcinoma (2 papers, 2012 to 2014). An infiltrating adenocarcinoma that arises from the epithelial cells of the pancreas. "We investigated the mRNA and protein expression of ERCC1 and RRM1 by RT-PCR and immunohistochemistry (IHC) in formalin-fixed, paraffin-embedded pancreatic ductal carcinoma (PDA) tissues." (PMID 22436573, 2012).
triple-negative breast carcinoma (2 papers, 2019 to 2022). An invasive breast carcinoma which is negative for expression of estrogen receptor (ER), progesterone receptor (PR), and human epidermal growth factor receptor 2 (HER2). "A study showed that high expression of ERCC1 in triple-negative breast cancer was associated with poor patient prognosis." (PMID 36338712, 2022). "In patients with triple-negative breast cancer, high expression of ERCC1 was observed in the DNA repair pathway, thereby altering the sensitivity of cancers to chemotherapeutic drugs and DNA damage inhibitors." (PMID 36338712, 2022). "High ERCC1 expression was observed in patients with ER-positive breast cancer, whereas the ERCC1 expression was low in patients with triple-negative breast cancer." (PMID 36338712, 2022). "A previous, small study suggested that ERCC1 protein levels may be low in triple negative breast cancers (TNBCs)." (PMID 31405143, 2019).
Xeroderma pigmentosum complementation group D (2 papers, 2006 to 2021). Xeroderma pigmentosum complementation group D (XPD) is a subtype of xeroderma pigmentosum (XP; see this term), a rare photodermatosis predisposing to skin cancers. "In the NER pathway, ERCC1 protein and xeroderma pigmentosum complementation group D (XPD) together form a heterodimer of ERCC1-XPD, which is a 5ʹ-3ʹ DNA restricted endonuclease in NER, and also functions in DNA repair connection and inner chain cross repair." (PMID 34148553, 2021). "Important members of the NER pathway, namely excision-repair-cross-complementing gene 1 and 2 (ERCC1 and ERCC2), the latest also named Xeroderma pigmentosum complementation group D (XPD) exhibit several polymorphic sites." (PMID 16317430, 2006).
alcohol use disorder (1 paper, 2012). "In AUD subjects Ercc1 expression was nominally correlated with the age of onset of the alcohol use disorder and robustly and significantly correlated with the volume of the supramarginal gyrus in the left inferior parietal lobe region." (PMID 23095216, 2012).
alopecia (1 paper, 2019). Hair loss usually from the scalp. "Grades III–IV vomiting, nausea, and alopecia could be partly explained by the presence of specific ERCC1/2, MDR1, GSTP1, and BLMH genotypes (p < 0.05)." (PMID 30914949, 2019). "Grades III–IV vomiting, nausea and alopecia could also be partly explained by the presence of specific ERCC1/2, MDR1, GSTP1, and BLMH genotypes." (PMID 30914949, 2019).
Anxiety (1 paper, 2021). Intense feelings of nervousness, tension, or panic often arise in response to interpersonal stresses. "ERCC1 rs3212986-rs11615 haplotype was associated with emotional function, cognitive function, somatic function, loss of appetite, dysphagia and anxiety scores." (PMID 34284736, 2021). "In other words, patients with ERCC1 rs11615 A allele had better emotional functions, while patients with ERCC1 rs3212986 A allele had severer anxiety than those with the allele." (PMID 34284736, 2021). "ERCC1 rs11615 was associated with emotional functioning (P = 0.027), and ERCC1 rs3212986 was associated with anxiety scores (P = 0.018)." (PMID 34284736, 2021). "ERCC1 rs3212986-rs11615 AG haplotype was associated with poor cognitive function and somatic function, severe symptoms of loss of appetite, and dysphagia, while LC patients having a copy of CA haplotype had better emotional functions, mild dysphagia, and lower anxiety score." (PMID 34284736, 2021). "After adjustment for environmental factors, SNPs and haplotypes of ERCC1 and ERCC2 were associated with different domains of QoL, depression and anxiety in LC patients." (PMID 34284736, 2021). "This study showed that ERCC1 rs3212986, ERCC1 rs3212986-rs11615, ERCC2 rs13181-rs3916874-rs238416 were associated with anxiety or depression in LC patients." (PMID 34284736, 2021). "SNPs and haplotypes of ERCC1 and ERCC2 were associated with different domains of QoL, depression and anxiety in LC patients." (PMID 34284736, 2021). "In other words, patients with ERCC1 rs11615 A allele had a better emotional function, while patients with ERCC1 rs3212986 A allele had severer anxiety than those without the allele." (PMID 34284736, 2021). "The results showed that ERCC1 rs11615 was significantly correlated with emotional function (environment adjusted beta = 6.85, Bonferroni adjusted P = 0.027), and ERCC1 rs3212986 was significantly correlated with anxiety score (environment adjusted beta = 3.41, Bonferroni adjusted P = 0.018)." (PMID 34284736, 2021). "The current study is intended to explore the relationship between SNPs and haplotypes of ERCC1 and ERCC2 and the QoL, depression and anxiety status of patients with LC." (PMID 34284736, 2021). "The current study is intended to examine the effect of SNPs and haplotypes of ERCC1 and ERCC2 on the QoL, depression and anxiety of LC patients with demographic and clinical characteristics correction." (PMID 34284736, 2021). "However, the patients with ERCC1 rs3212986 A allele could not effectively relieve the symptoms due to poor chemotherapy effect, and their cognitive and physical functions were affected, which led to a higher anxiety level." (PMID 34284736, 2021).
Autoimmunity (1 paper, 2018). The occurrence of an immune reaction against the organism's own cells or tissues. "The presence of nucleic acids in the cytosol represents a danger signal activating the cytosolic surveillance system but cells develop strategies to avoid an excessive immune response leading to autoimmunity: endo- and exonucleases such as MUS81, ERCC1-XPF, DNaseII, and TREX155–58." (PMID 30523277, 2018).
bladder tumors (1 paper, 2012). "Of 93 bladder tumors, 54 (58.1%) were ERCC1 positive and 39 (41.9%) were ERCC1 negative." (PMID 22616552, 2012).
carcinoids (1 paper, 2012). "High expression of Excision Repair Cross Comlement Group 1 (ERCC1) in typical carcinoids might be predictive for platin-based therapies and ERCC1 seems to have a prognostic impact in lung carcinoids." (PMID 24213466, 2012).
choriocarcinoma (1 paper, 2020). An aggressive malignant tumor arising from trophoblastic cells. "The highest XPA and ERCC1 expression was found in TE, with decreasing amounts in yolk sac tumours and choriocarcinoma." (PMID 31906898, 2020).
colorectal adenocarcinoma (1 paper, 2023). The most common type of colorectal carcinoma. "Immunohistochemical analysis showed cytoplasmic expression of ERCC1 in 52.8% of colorectal adenocarcinoma patients included in the present study." (PMID 37510370, 2023). "ERCC1 was methylated in 44.6% of colorectal adenocarcinoma while MGMT was methylated in 69% of cases." (PMID 37510370, 2023). "IHC analysis revealed that ERCC1 staining was noted in 52.8% of colorectal adenocarcinoma and inversely related to distant metastasis and cancer recurrence." (PMID 37510370, 2023). "Therefore, a significant difference in ERCC1 and MGMT methylation between normal tissues and colorectal adenocarcinoma was reached (p ≤ 0.001)." (PMID 37510370, 2023).
coronary artery atherosclerosis (1 paper, 2017). "Excision repair cross-complementing 1 (ERCC1) gene encodes ERCC1 protein, which is mainly responsible for the repair of DNA damage in different diseases including coronary artery atherosclerosis by acting as a rate-limiting element in nucleotide excision repair (NER)." (PMID 28743890, 2017). "Therefore, combined with the association of SNP rs11615 with ERCC1 expression, we speculated that SNP rs11615 might accelerate the progress of coronary artery atherosclerosis." (PMID 28743890, 2017). "Taken together, SNP rs11615 in ERCC1 gene might confer susceptibility to CAD and severity of coronary atherosclerosis in a Chinese Han population." (PMID 28743890, 2017).
ductal adenocarcinoma (1 paper, 2014). "Expression of MGMT, ERCC1, hMSH2, and hMLH1 had no obvious correlation with the size of tumor mass and differentiation degree of ductal adenocarcinoma (P >0.05)." (PMID 24502441, 2014). "The positive rates of MGMT, ERCC1, hMSH2, and hMLH1 were significantly lower in ductal adenocarcinoma than those in non-cancerous tissues of group B (P <0.05)." (PMID 24502441, 2014). "No statistical differences were found among the positive rates of MGMT, ERCC1, hMSH2, and hMLH1 in ductal adenocarcinoma and non-cancerous pancreatic tissues of group A (P >0.05)." (PMID 24502441, 2014). "The positive rates of MGMT, ERCC1, hMSH2, and hMLH1 were significantly lower in ductal adenocarcinoma than those in non-cancerous pancreatic tissues in group A + group B (P <0.01 or P <0.05)." (PMID 24502441, 2014).
endothelial dysfunction (1 paper, 2021). In vascular diseases, endothelial dysfunction is a systemic pathological state of the endothelium (the inner lining of blood vessels) and can be broadly defined as an imbalance between vasodilating and vasoconstricting substances produced by (or acting on) the endothelium. "Whole body Ercc1Δ/- mice are characterized by a combination of a reduced ageing vasodilator response to NO and endothelial dysfunction, while in endothelium-specific Ercc1 KO mice (EC-KO), only the latter was the case." (PMID 34504640, 2021).
ependymoma (1 paper, 2018). A WHO grade II, slow growing tumor of children and young adults, usually located intraventricularly. "We found that proteins involved in DNA synthesis (e.g. RRM1), transcription (TOPO1), and repair (ERCC1) are enriched in ependymoma." (PMID 29487694, 2018). "This ependymoma cohort showed minimal alterations in gene amplifications and mutations but had high expression rates of DNA synthesis and repair enzymes such as RRM1 (47%), ERCC1 (48%), TOPO1 (62%) and class III β-tublin (TUBB3) (57%), which are also all associated with chemoresistance." (PMID 29487694, 2018). "Notably, ependymomas frequently overexpressed proteins implicated in DNA synthesis, transcription, and repair and/or drug resistance, including BCRP (5/7 [71%]), RRM1 (14/30 [47%]), ERCC1 (13/25 [48%]), TUBB3 (12/21 [57%]), TOPO1 (23/37 [62%]), and MRP1 (8/14 [43%])." (PMID 29487694, 2018).
Erythema (1 paper, 2025). Redness of the skin, caused by hyperemia of the capillaries in the lower layers of the skin. "Polymorphisms in DNA repair genes (e.g., XRCC2, ERCC2, and ERCC1) and inflammatory mediators like IFNG were most linked to acute adverse effects, including erythema, desquamation, and oedema." (PMID 40507362, 2025).
experimental autoimmune encephalomyelitis (1 paper, 2023). An autoimmune demyelinating disease of the central nervous system that is produced experimentally in animals by the injection of homogenized brain or spinal cord in Freund's adjuvant. "Lastly, it is notable that 3 mouse models of brain disease that are alleviated with hypoxia—Ndufs4 KO, experimental autoimmune encephalomyelitis, and Ercc1 Δ/-—demonstrate severe neuroinflammation as a major feature of their pathology." (PMID 37220109, 2023).
fibrosarcoma (1 paper, 2014). A malignant mesenchymal fibroblastic neoplasm affecting the soft tissue and bone. "All pancreas of group C had positive expression of MGMT, ERCC1, hMSH2, and hMLH1 and two cases of fibrosarcoma showed a negative expression." (PMID 24502441, 2014). "The fibrosarcoma had negative expression of MGMT, ERCC1, hMSH2, and hMLH1, while pancreas of group C had positive expression of MGMT, ERCC1, hMSH2, and hMLH1." (PMID 24502441, 2014).
gastric cardia adenocarcinoma (1 paper, 2012). A carcinoma that arises from glandular epithelial cells of the cardia of stomach. "Patients with 2–3 ERCC1 risk genotypes had significant increased risk (adjusted OR = 1.56, 95% CI = 1.27–1.93), compared with those with 0–1 ERCC1 risk genotypes, and this risk was more significantly in subgroups of never drinkers, non-gastric cardia adenocarcinoma (NGCA) and clinical stage I+II." (PMID 23166636, 2012).
Glucose intolerance (1 paper, 2022). Glucose intolerance (GI) can be defined as dysglycemia that comprises both prediabetes and diabetes. "On the other hand, ERCC1 gene was reported to have an impact on glucose intolerance in a progeroid mouse model with ERCC1 deficiency, resulting in fat loss and IR by triggering an autoinflammatory response." (PMID 35627777, 2022).
gynecological cancers (1 paper, 2022). "The prognostic value of ERCC1 expression in gynecological and non-gynecological cancers and its association with chemotherapy resistance have been investigated by various groups." (PMID 35147976, 2022).
Hyperglycemia (1 paper, 2025). An increased concentration of glucose in the blood. "Further, defective ERCC1-XPF causes increased GLUT1 and GLUT3-mediated hepatocyte glucose uptake, and the resulting hyperglycemia activates pro-inflammatory responses via mTOR." (PMID 40065360, 2025).